TLR4 (toll like receptor 4)
Diseases named in the same sentence as TLR4 in open-access papers (continued):
Sharing a sentence is not in itself a finding about the gene and the disease.
emphysema (continued). "Furthermore, we measured TLR4, which is involved in mtDNA fragmentation, and whose deficiency causes age-dependent emphysema." (PMID 35159179, 2022). "In the present study, we confirmed that TLR4−/− mice were susceptible to age‐related emphysema." (PMID 30790400, 2019). "Of note, lung Ec‐TLR4‐sil mice showed increases in lung compliance and chord lengths, to a similar degree to Ubi‐TLR4‐sil mice, indicating that lung Ec‐TLR4‐sil is sufficient to cause emphysema." (PMID 30790400, 2019). "Encouragingly, we verified various well-known mechanistic changes associated with emphysema development, such as NF-κB signaling and TLR4 signaling, as well as increased levels of TNF-α, CSF2, and non-predicted but related interleukins, MPO, and MMP-9 by means of proteomic analysis." (PMID 25962837, 2015). "Specifically, a causal role for TLR4, the prototypical innate immune pathogen recognition receptor, in the development of emphysema has been suggested from animal studies whereby TLR4 deficiency leads to spontaneous emphysema as a result of excessive oxidant activity." (PMID 24205107, 2013). "First, the causal relationship between down-regulated TLR4 expression and emphysema is ambiguous." (PMID 23170858, 2012). "Moreover, TLR4 deficiency in the lung leads to spontaneous emphysema in animals, which is associated with an oxidant/antioxidant imbalance." (PMID 23170858, 2012). "In the present study, we hypothesized that TLR4 expression differs among people and that this can be associated with the emphysema or airflow limitation." (PMID 23170858, 2012). "To test this hypothesis, we analyzed the association between emphysema severity, TLR4 expression in lung tissue and emphysema." (PMID 23170858, 2012). "We analyzed the association of TLR4 expression, airflow limitation and emphysema in smokers." (PMID 23170858, 2012). "Further studies using appropriate animal models may verify the roles of TLR4 rs11536889 polymorphism in the pathogenesis of emphysema." (PMID 22251849, 2012). "Theoretically, TLR4 deficiency may partially protect against smoke-induced emphysema, because TLR4 deficiency partially prevents smoke-induced influx of dendritic cells, lymphocytes, and neutrophils." (PMID 23170858, 2012). "Moreover, TLR4-knockout mice (Tlr4 − /− mice) spontaneously develop emphysema, associated with an oxidant/antioxidant imbalance, due to increased Nox3 gene expression and elastin degradation." (PMID 20169003, 2009). "Recent evidence also implicates TLR4 deficiency in oxidant induced lung damage and emphysema." (PMID 18034897, 2007). "Thus, an impaired defense owing to TLR4 deficiency combined with repeated inflammation may result in the development of emphysema." (PMID 23170858, 2012). "Although the downstream signaling of TLR4 has not been precisely identified, it has been confirmed that alterations in TLR4 expression are pivotal in the development of emphysema." (PMID 38001481, 2023). "These emphysema symptoms are notably influenced by the level of TLR4 expression in lung endothelial cells." (PMID 38001481, 2023). "Lung Ec‐p16INK4a‐silencing prevented TLR4−/− induced emphysema, revealing a new functional role for p16INK4ain lungs." (PMID 30790400, 2019). "Our current findings support a previously unrecognized role of lung Ec‐TLR4 in maintaining normal lung integrity and thus preventing early emphysema." (PMID 30790400, 2019). "We proceeded to generate mice that express the human TLR4 (hTLR4) transgene, in the presence of DOX, only in Ec (Ec‐TLR4‐reconstit) to confirm the role of Ec TLR4 in modulating age‐related emphysema in TLR4 ‐/‐ mice." (PMID 30790400, 2019). "As further evidence that TLR4‐deficiency recapitulates, to some extent, human COPD and CS‐induced emphysema, we found that HDAC2 mRNA expression significantly decreased in lungs from TLR4−/− mice compared to WT." (PMID 30790400, 2019).
emphysema (continued). "Lung Ec‐silencing of TLR4 in wild‐type mice induced emphysema, highlighting the specific and distinct role of Ec‐expressed TLR4 in maintaining lung integrity." (PMID 30790400, 2019). "To further understand the role of TLR4 in age‐related emphysema, we extended the time course to older ages up to 12 months and found that TLR4−/− mice exhibited increased lung volumes and chord lengths at significantly earlier ages than age‐matched WT mice." (PMID 30790400, 2019). "Additional investigation is needed to study the clinical implications of down-regulated TLR4 expression in patients with severe emphysema." (PMID 31847115, 2019). "TLR4 plays an important role in lung structure maintenance and smoking-induced emphysema and stimulates low-grade activation of the innate immune system, which is required for lung structural stability." (PMID 31640653, 2019). "The activation of TLR4 is a critical upstream signalling event in the smoke-induced induction of the collagenase MMP-1 in emphysema development." (PMID 31182072, 2019). "Lastly, we show a functional role for Ec‐p16INK4a in emphysema by demonstrating that lung‐targeted Ec‐p16INK4a in vivo blocks specific SASP induction and, importantly, prevents emphysema in TLR4−/− mice." (PMID 30790400, 2019). "An and colleagues reported that TLR4 exerts a protective role in CS-induced emphysema development by reducing the autophagic pathway." (PMID 28028752, 2017). "We predicted 39 molecular changes mostly related to inflammatory processes including known key emphysema drivers such as NF-κB and TLR4 signaling, and increased levels of TNF-α, CSF2, and several interleukins." (PMID 25962837, 2015). "By contrast, the spontaneous development of emphysema in Tlr4−/− mice strongly correlated with elevated oxidative protein carbonylation levels and increased alveolar cell apoptosis by 6 months of age." (PMID 24205107, 2013). "In contrast, TLR4 has been reported to mediate pro-apoptotic signaling in airway epithelial cells of COPD smokers in a different setting (smoke related) to the spontaneous emphysema observed in Tlr4−/− mice." (PMID 24205107, 2013). "Since it has also been shown that MyD88 (like TLR4) is required to prevent the onset of emphysema, these observations reveal a differential requirement for Mal and MyD88 in maintaining normal lung architecture via TLR4 signaling." (PMID 24205107, 2013). "When MMP-1 is present, as is seen in both human emphysema as well as in the smoke-exposed rabbit, TLR4 activation by cigarette smoke ultimately leads to expression of the collagenase MMP-1." (PMID 23450717, 2013). "The TLR4 low expresser group included a higher number of severe-stage emphysema cases; the proportions of severe compared with mild emphysema in the high, intermediate, and low expressers were 43.8% (7/16), 72.0% (18/25), and 83.4% (10/12) (P = 0.007)." (PMID 23170858, 2012). "The mean emphysema score increased as TLR4 expression decreased; the mean emphysema scores of the high, intermediate, and low expressers were 3.63 ± 4.77, 4.92 ± 4.60, and 8.33 ± 5.26, respectively (P = 0.02)." (PMID 23170858, 2012). "Forced expiratory volume in one second per forced vital capacity (FEV1/FVC) increased (P=0.03) and emphysema score decreased (P=0.01) as TLR4 expression increased." (PMID 23170858, 2012). "In this case-control study, we investigated the association between TLR4 SNPs and COPD in Japanese subjects, with a focus on the emphysema phenotype." (PMID 22251849, 2012). "TLR4 loss causes the activation of a new NADPH oxidase (Nox) in the lungs and endothelial cells, which increases oxidant generation and elastolytic activity altering the normal structure of lung tissue and inducing emphysema." (PMID 38013266, 2023). "In comparison to WT mice, it was observed that emphysema symptoms manifested in an age-dependent manner without external stimulation in TLR4-deficient mice." (PMID 38001481, 2023).
emphysema (continued). "Remarkably, studies have shown that TLR4 deficiency in mice led to spontaneous emphysema, without a notable increase in inflammatory cell numbers, while also triggering elevated endogenous Nox3 (NADPH Oxidase 3) activity in endothelial cells." (PMID 37240069, 2023). "Additionally, histologic evaluation revealed enlargement of the airspaces accompanied by loss of the normal airspace architecture in Ec‐TLR4‐sil mice and Ub‐TLR4‐sil, characteristic of emphysema." (PMID 30790400, 2019). "Next, we investigated the role of lung‐specific Ec‐TLR4 silencing in emphysema." (PMID 30790400, 2019). "Here we report a differential requirement for TLR2 and TLR4 in protecting against apoptosis and regulating the oxidative balance in the lung, since Tlr2−/− mice display normal pulmonary oxidative stress and apoptosis levels, and also fail to develop emphysema." (PMID 24205107, 2013). "Strikingly, although Mal deficiency in the lungs of mice promoted increased alveolar cell apoptosis comparable to that observed upon TLR4 deficiency, oxidative stress levels in Mal−/− mice were normal, and Mal−/− mice did not develop emphysema." (PMID 24205107, 2013). "Consistent with a previous study, histological evaluation of lung sections from unchallenged Tlr4−/− mice at 6 months of age revealed emphysema as characterized by enlargement of the distal air spaces and destruction of normal alveolar architecture without any obvious inflammation." (PMID 24205107, 2013). "We therefore next determined whether the differential role of TLR4 and TLR2 in protecting against the onset of emphysema correlated with alterations in the oxidant/antioxidant ratio in Tlr4−/− and Tlr2−/− mice." (PMID 24205107, 2013). "However, despite normal oxidative protein carbonylation levels in the lungs of emphysema-free Mal−/− mice, these mice displayed increased levels of apoptosis comparable to those observed in emphysematous Tlr4−/− mice." (PMID 24205107, 2013). "Although TLR4 deficiency causes an oxidative imbalance in the lung leading to emphysema in a MyD88-dependent manner, the role of Mal in emphysema has not been studied." (PMID 24205107, 2013). "While genetic ablation of the TLR4/MyD88 signaling axis in mice leads to pulmonary cell death and oxidative stress culminating in emphysema, the involvement of Mal, as well as TLR2 which like TLR4 also signals via MyD88 and Mal, in the pathogenesis of emphysema has not been studied." (PMID 24205107, 2013). "FEV1/FVC increased (P=0.03) and emphysema score decreased (P=0.01) as TLR4 expression increased." (PMID 23170858, 2012). "Our findings can make an important contribution on the relationship between innate immunity and COPD, because they show that down-regulated TLR4 expression in the lung may be related to emphysema in humans, as in animals." (PMID 23170858, 2012). "Overall, TLR4 exerts a protective role with respect to smoke-induced emphysema development." (PMID 23170858, 2012). "Previous reports showing that TLR4 knockdown induces spontaneous emphysema also support this idea." (PMID 23170858, 2012). "We showed that a down-regulated TLR4 expression in the lung can be a predictor or biomarker of emphysema in smokers or biomarker of emphysema, as patients with down-regulated TLR4 expression had a greater probability of developing emphysema and airflow limitation." (PMID 23170858, 2012). "An association between innate immunity including Toll-like receptors (TLRs) and COPD is reported recently; TLR4 deficiency in lung can cause emphysema in animals, which is not evident in humans." (PMID 23170858, 2012). "At present, no other additional SNPs of the TLR4 gene have been reported to be associated with emphysema or COPD in Japanese or other populations worldwide." (PMID 22251849, 2012). "We compared TLR4 expression between inbred rats with and without emphysema to exclude the possibility that acquired emphysema development itself caused by smoking can affect TLR4 expression." (PMID 23170858, 2012).
emphysema (continued). "Interestingly, TLR4 deficiency resulted in spontaneous emphysema in mice in the absence of a significant increase in inflammatory cell numbers and increased endogenous Nox3 activity in endothelial cells." (PMID 35055174, 2022). "Furthermore, we propose that both excessive pulmonary apoptosis and oxidative stress caused by the absence of TLR4 are required for the pathogenesis of emphysema." (PMID 24205107, 2013). "Interestingly, however, emphysema-free Mal−/− mouse lungs showed an elevated level of apoptosis at 6 months of age, comparable to that observed in the lungs of emphysematous Tlr4−/− mice." (PMID 24205107, 2013). "However, previous studies and our study have shown that TLR4 deficiency does not protect against the development of emphysema." (PMID 23170858, 2012). "Consistent with the early‐onset of emphysema in TLR4−/− mice, we detected increased SA‐β‐gal activity, a marker for cellular senescence, in TLR4−/− mice lung compared to that in the WT lung at 6 month." (PMID 30790400, 2019). "The pattern recognition receptor toll-like receptor-4 (TLR4), mediated through the NADPH oxidase (NOX) pathway, is another important component in the oxidative stress pathway critical in emphysema development." (PMID 23450717, 2013). "In addition, CS-induced emphysema-like alveolar enlargement, apoptosis, and impaired lung function were enhanced in TLR2−/− mice and were decreased in TLR4−/− mice." (PMID 38811459, 2024). "Epi‐TLR4‐reconstition also prevented emphysema but not to the full extent observed in Ec‐TLR4‐reconstit." (PMID 30790400, 2019). "Based on our previous report that TLR4 bone marrow reconstitution had no impact on emphysema or survival during oxidant lung injury, we focused on TLR4 reconstitution in structural cells rather than circulating cells." (PMID 30790400, 2019). "Here, we sought to delineate nonmicrobial roles for TLR4 in preventing emphysema using tissue‐ and cell‐specific targeting of TLR4 in vivo, and to translate our findings to primary human lung microvascular Ec (hLMVEC)." (PMID 30790400, 2019). "Interestingly, we found p16INK4a mRNA expression was suppressed in lungs from Ec‐TLR4‐reconstit X TLR4−/− mice compared to TLR4−/−, suggesting that Ec‐TLR4 negatively regulates p16INK4a expression in lungs that exhibit early emphysema." (PMID 30790400, 2019). "By employing an in vivo genetic approach, we reveal here that unlike the spontaneous pulmonary emphysema which developed in Tlr4−/− mice by 6 months of age, the lungs of Tlr2−/− mice showed no physiological or morphological signs of emphysema." (PMID 24205107, 2013). "In this paper, we now provide definitive genetic proof that Mal is not required for the function of TLR4 in protecting against the onset of emphysema." (PMID 24205107, 2013). "Oxidative imbalance is a key process associated with the development of emphysema in both COPD patients and mouse disease models, including mice lacking TLR4." (PMID 24205107, 2013). "A pilot study showed that TLR4 expression was lower in five patients with emphysema than in the other five without emphysema." (PMID 23170858, 2012). "Smoke-induced emphysema itself did not appear to alter TLR4 expression; therefore TLR4 expression seems to affect emphysema development or progression, rather than vice versa." (PMID 23170858, 2012). "At present, no TLR4 SNPs have yet been reported with the emphysema phenotype of COPD in Japanese subjects." (PMID 22251849, 2012). "Differences in TLR4 expression in the bronchial epithelium in different individuals may reflect the morphological and clinical and functional heterogeneity of COPD, including the development of emphysema and exacerbations." (PMID 35055174, 2022).
emphysema (continued). "CS-related TLR4 signaling was shown to increase MMP-1, a crucial actor in emphysema, in a MyD88- and IRAK1-dependent manner, while CS-exposed TLR4–/– mice were protected from emphysema, impaired lung function, airway fibrosis, and collagen deposition in small airways as compared with wild-type mice." (PMID 34248677, 2021). "However, concomitant injection with the toll-like receptor 4 (TLR4) ligand lipid A into rats could decrease endothelial cell apoptosis and reduce the incidence of emphysema." (PMID 33546691, 2021). "Thus, it is possible that in the absence of TLR4, ROS reaches harmful levels and ultimately leads to cellular apoptosis and emphysema." (PMID 26617525, 2015). "In addition, we reveal that Mal differentially facilitates the anti-apoptotic, but not oxidant suppressive, activities of TLR4 in the lung, both of which appear to be essential for TLR4 to prevent the onset of emphysema." (PMID 24205107, 2013). "However, our data showed that smoke-induced emphysema itself did not affect TLR4 expression, providing more evidence that down-regulated TLR4 expression results in emphysema." (PMID 23170858, 2012). "In light of the absence of an emphysema phenotype in the lungs of Mal−/− mice, unlike the emphysema observed in Tlr4−/− mice, we next assessed whether the levels of oxidative stress and apoptosis (both elevated in Tlr4−/− lungs) were also unaltered in Mal−/− lungs." (PMID 24205107, 2013).
systemic inflammatory response syndrome (25 papers, 2010 to 2026). SIRS is a serious condition related to systemic inflammation, organ dysfunction, and organ failure. "The TLR4 Asp299Gly haplotype has also been associated with an increased incidence of systemic inflammatory response syndrome." (PMID 41295183, 2025). "TLR4 recognizes these molecules, stimulating innate and adaptive immune responses and causing systemic inflammatory response syndrome (SIRS)." (PMID 37760794, 2023). "Interfering with LPS binding by the co-receptor protein myeloid differentiation factor 2 (MD-2) represents a useful approach for down-regulation of MD-2·TLR4-mediated innate immune signaling, which is implicated in the pathogenesis of a variety of human diseases, including sepsis syndrome." (PMID 25394365, 2015). "Over the past two decades, the downregulation of TLR4 signaling has been shown to be potentially beneficial in the treatment of arthritis, viral infection-related pathology, and sepsis syndrome." (PMID 37630200, 2023). "In these acute challenge models, such as is also produced by high dose LPS injection, MRP8/14 was suggested to act as a danger signal enhancing the cytokine response of LPS via TLR4, thereby potentiating the harmful systemic inflammatory response syndrome." (PMID 23133376, 2012). "Juxtapose, in the conditions of unresolved inflammation, TLR4 and caspase-4/11 activation can result in the amplified innate immune signaling, systemic overexpression of the pro-inflammatory mediators and pyroptosis which prompts the onset of sepsis syndrome and a fatal septic shock." (PMID 33329561, 2020). "However, dysfunction in the tightly coordinated mechanisms of TLR4-mediated signaling can result in the uncontrolled upregulation of local and systemic inflammatory responses, leading to acute or chronic diseases, the most devastating of which are sepsis syndrome and acute lung injury." (PMID 37630200, 2023). "Among patients with systemic inflammatory response syndrome (SIRS), urinary TLR4 was higher in patients with co-occurring kidney dysfunction." (PMID 38139297, 2023). "TLR4 is responsible for recognizing endotoxin or LPS from gram-negative bacteria and initiating the systemic inflammatory response syndrome." (PMID 30225247, 2018).